TNF (tumor necrosis factor)
Diseases named in the same sentence as TNF in open-access papers (continued):
Sharing a sentence is not in itself a finding about the gene and the disease.
Stroke (continued). "However, the increases of TNF-α release by lower doses of atorvastatin were more robust in case of stroke patient derived monocytes, as compared to healthy donor derived monocytes." (PMID 33959001, 2021). "We tested the effects of MEDS-23 on levels of IL-6, PGE2 and TNF-α in the brains of post-stroke rats to elucidate whether it exerts anti-inflammatory effects that may explain its ability to alleviate the elevated BT (fever) observed in these animals." (PMID 35053779, 2021). "Although further studies in a larger patient population are needed, TNF-α may be a potential biomarker of cognitive impairment/functional status in stroke cases." (PMID 34433866, 2021). "In order to examine the phenotypic alteration of astrocytes in the co-culture with microglia, GFAP+ astrocytes were exposed to oxygen glucose deprivation (OGD) conditions, similar to the stroke microenvironment, in combination with the inflammatory cytokines TNF-α and IFN-γ." (PMID 34445510, 2021). "Third, IFN-γ is a potent inducer of other pro-inflammatory cytokines, such as IL-6, IL-1β and TNF-α, which may further the inflammatory response following the original stroke insult." (PMID 33919670, 2021). "Salivary TNF-α, IL-6, and IL-10 may be potential non-invasive biomarkers that distinguish stroke patients from controls with high sensitivity and specificity." (PMID 34433866, 2021). "In the past, there have been many attempts to treat stroke by intervention on the peripheral immune system, mainly through the intervention of cytokine receptors, such as TNF-α, IL-1, IL-6 and IL-10, while most of the attempts failed to be translated into clinical application." (PMID 34876161, 2021). "All anti-TNF-α agents show protection against stroke brain injury." (PMID 34073455, 2021). "Circulating biomarkers which constitute the typical lipid patient profile (LDL-C, TC, triglyceride, Ox-LDL, Lp-PLA2), inflammatory biomarkers such as hs-CRP, TNF-α, IL-6, adipokines (adiponectin, leptin, FABP4) and homocysteine are related to the high risk of future stroke." (PMID 34829489, 2021). "Thus, it appears that the dual role depends on the source of TNF-α, with microglial-derived TNF-α being neuroprotective in stroke." (PMID 35008440, 2021). "During the early hours after the onset of stroke, there are increments of various cytokines such as interleukin-1 beta (IL-1β), interleukin-1 receptor antagonist (IL-1ra), interleukin-6 (IL-6), IL-8, IL-10, and tumor necrosis factor alpha (TNF-α)." (PMID 34072449, 2021). "Further analysis showed that BHD could act on many biological processes of IS and had an influence on the outcome of stroke through TNF, PI3K-Akt, MAPK, and NF-kappa B signaling pathway." (PMID 33727944, 2021). "Moreover, preclinical studies have shown that TXNIP also increases the expression level of TNF-α in hyperglycemic condition with tPA-reperfusion in stroke." (PMID 34681207, 2021). "Astrocytes can increase neutrophil recruitment via CXCL chemokines, express adhesion molecules for leukocyte recruitment, which can be stimulated by IL-1, and further intensify pro-inflammation by producing cytokines such as IL-1α and TNF-α after ischemic and reperfusion injury of stroke." (PMID 34502395, 2021). "The core targets of DZSM for stroke are TNF, AKT1, VEGFA, and IL-1β, which are highly correlated." (PMID 34754318, 2021). "Intriguingly, both IMAT and pro-inflammatory adipokines, TNFα and IL-6, were found to be locally increased in the paretic leg of stroke survivors, suggesting that the inflammatory milieu could be locally conditioned by IMAT quantity." (PMID 34025446, 2021). "Of particular note is salivary TNF-α, which may indicate cognitive/physical impairment in post-stroke individuals." (PMID 34433866, 2021). "Interleukin (IL)-1beta, TNF-alpha, and IL-4 mRNA levels were higher, while IL-10 mRNA levels were reduced in total monocytes from patients versus controls, at either 24 h or 48 h after stroke." (PMID 34201498, 2021).
Stroke (continued). "Moreover, the serum levels of TNF-α and IL-6 were markedly increased in the subacute phase of stroke, which were reversed by QSYQ (600 mg/kg)." (PMID 33953667, 2021). "In a MCAO model of stroke, acute stress was shown to increase brain ischemic damage, the effect of stress being mediated at least partially by pro-inflammatory cytokines IL1β and TNFα." (PMID 34948340, 2021). "A large fraction of these genes such as Hmgb2, TNF and IL-11 were pro-inflammatory factors Cluster two genes such as Ctss and PTPN18are either peptidases or proteases that were expressed at 3 days and peaked 7 days after stroke onset." (PMID 34094642, 2021). "M1 phenotype microglia can produce a variety of mediators, including inducible nitric oxide synthase (Nos2), C-X-C motif chemokine 10 (Cxcl10, as known as IP10), tumor necrosis factor (Tnfα), and cyclooxygenase-2 (Cox2) to induce oxidative stress, inflammation, and necroptosis after stroke." (PMID 34457033, 2021). "TNF-α is present at high levels in various neurodegenerative disorders such as Parkinson’s disease, Alzheimer’s disease, Huntington’s disease, amyotrophic lateral sclerosis, and stroke, where it is thought to play an important role as a proinflammatory agent." (PMID 32403417, 2020). "Several studies have shown that TNF-α affects the survival, differentiation, and proliferation of neural stem/progenitor cells, and contributes to neuroprotection and tissue regeneration in stroke, status epilepticus, and inflammation." (PMID 32403417, 2020). "Peri-spinal administration of the non-selective TNF antagonist etanercept provided benefits for post-stroke pain and improved cognitive dysfunction in chronic stroke patients, demonstrating the potential of anti-TNF inhibitors as anti-inflammatory treatment in ischemic stroke." (PMID 32503645, 2020). "However, the non-specific production in response to PMA of pro-inflammatory TNF-α by CD3+ lymphocytes at admission was related to poor stroke outcomes at 90 days even after adjusting for baseline stroke severity (OR 1.13, 95% CI 1.01–1.27, p = 0.041)." (PMID 32719588, 2020). "Within minutes after injury, injured neurons and glial cells in the core and penumbra of the stroke produce pro-inflammatory mediators, including interleukin-6 (IL-6), interleukin-1 β (IL-1β), and tumor necrosis factor-α (TNF-α), which activate both astrocytes and microglia." (PMID 32595496, 2020). "However, a few studies have shown that TNF-a synthesis is induced in neurons in some pathological situations, including stroke, intracerebral hemorrhage, spinal cord injury, and sciatic nerve injury." (PMID 32087723, 2020). "Fourth, since plasma IL-6 levels, TNF release ex vivo, and GC resistance depend on stroke severity, one common biological mechanism induced by brain injury could be responsible for all these phenomena." (PMID 32107751, 2020). "Interestingly, increases in the systemic inflammatory response measured by circulating TNF-α and IL-6 were observed along with changes in fecal microbiome at the acute stage of stroke." (PMID 33343283, 2020). "In stroke, the lesion develops quickly, prior to leukocyte infiltration, which may explain the importance of microglial-derived TNF on the final lesion size." (PMID 33153044, 2020). "The results showed that I/R induced obvious cerebral infarction and neurobehavioral defects, in parallel with histological aberrations and extensive signaling of proinflammatory cytokines, including tumor necrosis factor (TNF-α) and interleukin-6 (IL-6), in the stroke model." (PMID 32714088, 2020). "Hence, TNFα and IL-1β plasma level assessment can be useful not only for diagnosis of different stroke types, but also their severity and accompanying metabolic disorders." (PMID 31701356, 2020). "Altogether, this could suggest that the body’s response to ischemic stroke is to increase soluble TNFR1 levels capable of binding soluble TNF, which we know exerts detrimental effects in experimental stroke." (PMID 32503645, 2020).
Stroke (continued). "Furthermore, mice treated with A151 showed a dampened immune response to stroke, with reduced counts of neutrophils, microglia, and microglial production of IL‐6 and TNF‐α after MCAO." (PMID 32239625, 2020). "Importantly, TNFα, an inflammatory cytokine and potentiator of the necroptosis pathway, was significantly reduced in mice with stroke after Dabrafenib treatment." (PMID 33142926, 2020). "We can also observe that the quantity of TNF-α increases within 24 and 48 h following cerebral ischemia; the slight reduction, which takes place within 72 and 144 h after a stroke, is correlated with an improvement of the clinical conditions in patients during the acute stage of cerebral ischemia." (PMID 32899616, 2020). "At the time of stroke, rats treated with LV-UCP2 still showed a large UCP2 upregulation in the striatum, associated with increases in OPA1 and FIS1 protein levels, and reductions in PGC1-α, SOD2, TNFα mRNA levels and NRF2 protein levels." (PMID 32560241, 2020). "Additionally, p38 inhibition also protects cardiomyocytes from cellular injury upon myocardial ischemia and reperfusion, or reduces excessive inflammatory cytokine expression (e.g., TNF-α) and infarct size during stroke." (PMID 33178683, 2020). "In addition, when we compared the effect of captopril between stroke patient-derived Mo alone and their cocultures with MSCs, captopril showed an increase in IL-8 and TNF-α secretions from stroke patient-derived Mo alone." (PMID 32802081, 2020). "IL-1β and TNF-α are known to play a proinflammatory role after stroke and worsen stroke outcomes." (PMID 32802081, 2020). "Up-regulation of TNFα/NFκB signaling decreases tight junction protein expression leading to increased BBB permeability in pathological conditions such as stroke and here we report that this pathway is also involved in stress-induced BBB leakiness in the mouse NAc." (PMID 31974313, 2020). "In addition, when we compared the effect of atenolol between stroke patient-derived Mo alone and their cocultures with MSCs, higher doses of atenolol showed an increase in TNF-α secretions from stroke patient-derived Mo alone." (PMID 32802081, 2020). "Moreover, microglia activation is associated with upregulation of IL-1β and TNF-α, thus aggravating TBI and increasing the risk of stroke." (PMID 32454938, 2020). "As one of the key factors involved in stroke development, tumor necrosis factor alpha (TNF-α) can interfere with the normal function of the brain, affecting the permeability of the blood-brain barrier, and impairing the transmission of glutamic acid as well as the plasticity of the synapse." (PMID 32132924, 2020). "The researchers placed primary rat neuronal cells, co-cultured with astrocytes, in a HBOT chamber, and then exposed the cells to either tumor necrosis factor-alpha (TNF-α) or lipopolysaccharide to create a brain injury or stroke-like environment during the secondary cell death stage." (PMID 32867291, 2020). "The reduction in the LPS-induced production of NO and TNFα in CB2 knockout cultures was unexpected, since previous work demonstrated that CB2 activation is associated with decreased microglial inflammation and neuroprotection in a mouse stroke model." (PMID 31979350, 2020). "However, HDLs isolated from stroke patients were less prone to preventing gene changes induced by TNFα." (PMID 32708891, 2020). "Interestingly, the levels of MDA and TNF-α were significantly higher in stroke patients (p = 0.022 and 0.004, respectively)." (PMID 33126675, 2020). "Importantly, the ability of TNF‐α to regulate intestinal permeability is dependent on the induction of stroke as sham‐operated young mice with TNF‐α treatment were unaffected." (PMID 31199577, 2019). "ELISA analysis of TNF-α and IL-1β showed significantly higher concentrations of these pro-inflammatory cytokines in ischemic brain tissue of KO mice compared to WT controls at day 7 after stroke (p < 0.001)." (PMID 30777093, 2019).
Stroke (continued). "Furthermore, TNF-α serum- and cerebrospinal fluid-levels are increased in stroke patients and positively correlate to stroke severity." (PMID 30778120, 2019). "However, etanercept, a biologic TNF-α inhibitor, has been studied experimentally in the setting of traumatic brain injury and clinically for the treatment of stroke-induced neurological dysfunction." (PMID 31281252, 2019). "In addition to proliferation, a key function of microglia and MDMs in post-stroke inflammation is upregulation of inflammatory signaling molecules, such as TNFα and iNOS." (PMID 31138227, 2019). "Similar to TNF-α and IL-1β, Il-6 levels are elevated in CSF of severe stroke patients." (PMID 31291966, 2019). "The let‐7 family of microRNAs, which are also expressed by NSCs, have been shown to protect against neuroinflammation by regulating the expression of caspase 3, inducible nitric oxide synthase (iNOS), TNF‐α, and IL‐12, which improve stroke‐induced neurological deficits in mice." (PMID 30747485, 2019). "Finally, inflammatory factors, such as TNF-α and IL-1β, produced after stroke can activate inflammatory pathways, such as NF-κB, in stem cells, thereby enabling stem cells to acquire stronger immune regulation potential." (PMID 30700305, 2019). "However, TNFα expression after stroke was 1.8-fold lower in clenbuterol-treated mice compared to saline-treated mice, indicating that increased β2-adrenergic stimulation after stroke suppresses this pro-inflammatory cytokine." (PMID 31138227, 2019). "TNF signaling is one of the key players in stroke inflammation progression: inhibition of TNF signaling can rescue functional cortical plasticity impaired in early post-stroke period." (PMID 31772561, 2019). "The likely source of elevated TNF‐α in the colon of older poststroke mice is the damaged intestinal epithelium, as the immune composition of the gut and serum concentrations of this pro‐inflammatory cytokine remained unchanged after stroke." (PMID 31199577, 2019). "Stroke-induced release of pro-inflammatory mediators and cytokines leads to brain cell damage and apoptosis, specifically tied to increased levels of pro-inflammatory cytokines IL-6 and TNF-α." (PMID 31354401, 2019). "The knockdown of miR-181a enhanced the production of pro-inflammatory cytokines (TNF-α, IL-6, IL-1β, IL-8), and increased levels of the anti-inflammatory cytokine IL-10 result from miR-181 over-expression in a murine stroke model." (PMID 30953275, 2019). "The main proinflammatory cytokines in stroke are TNFα, IL-1β, and IL-6." (PMID 31544811, 2019). "Following a photochemically induced motor cortex stroke, treatment with DS2 at 0.1 mg/kg from 1 h post-stroke significantly decreased circulating tumor necrosis factor (TNF)-α, interleukin (IL)-17, and IL-6 levels, reduced infarct size and improved motor function in mice." (PMID 31736685, 2019). "Notably, we report higher expression of TNFα in Adrb2cKO animals after stroke, in which the β2-adrenergic receptor is specifically knocked out of microglia/MDMs." (PMID 31138227, 2019). "Moreover, elevated levels of IL‐6 and TNF‐α have been also found in stroke patients with depressive symptoms (Su, Chou, Tsai, & Hung, 2012)." (PMID 29484258, 2018). "The role of TNF-α in stroke is controversial and either deleterious or beneficial in stroke, depending on the local source of production (microglia, lymphocytes, astrocytes, or neurons), the timing poststroke, and the specific receptor subtype that is activated." (PMID 29736174, 2018). "In agreement with this, concentrations of TNFα were reduced in spleens after experimental stroke." (PMID 29872438, 2018). "Given the anti-inflammatory role of miR-424 in the brain of experimental stroke, we further examined TNF-α, IL-10 and IGF1 levels in plasma and determined whether an association existed between plasma cytokines and miR-424 levels." (PMID 29675290, 2018).
Stroke (continued). "Furthermore, activated astrocytes can produce an array of pro-inflammatory cytokines, including IL-1β and TNF-α, which promote inflammation after stroke." (PMID 29976213, 2018). "Stroke and cerebral ischemic damage induce high serum and brain levels of TNF-α." (PMID 29662435, 2018). "To determine whether exacerbated microglia activation could account for poor outcomes in older mice, we assessed TNF protein production after stroke, which is known to correlate with poor outcome." (PMID 29752550, 2018). "However, in TNF-KO mice, such inflammation induced by pMCAO was remarkably attenuated at day 1 after stroke." (PMID 29807527, 2018). "Finally, several molecules involved in acute phase response signaling pathway, including IL-6 or TNF-α, have been consistently related to acute ischemic stroke and stroke recurrence." (PMID 29414888, 2018). "A remarkable upregulation of TNF-α has been described to occur in the brain tissue following a stroke in both animal models and in patients which has been shown to induce cytoskeletal reorganization and decrease tight junction protein expression in endothelial cells." (PMID 29452577, 2018). "Interestingly, elevated TNF-α expression and further enhanced IL-6 levels were reported in stroke rats subjected to RIC pretreatment." (PMID 30115811, 2018). "Indeed engineering of a BBB crossing TNF-α inhibitor allowed to decrease infarct volume and to improve neurological outcome in a stroke experimental model." (PMID 30057552, 2018). "Similarly, the anti-TNF-α antibody Pl14 and the TNF synthesis inhibitor CNI-1493 also improve behavioral deficits in Lewis rats after stroke." (PMID 28115020, 2017). "Anti-TNF neutralizing antibodies and the inhibition of soluble TNF-α receptor type 1 have been reported to reduce ischemic damage and improve functional outcome after stroke." (PMID 28168001, 2017). "In the same study, these findings were associated with upregulation of free radical scavengers such as glutathione and manganese superoxide dismutase, reduced activity of the proapoptotic protein caspase 3, and downregulation of IL-1β, IFN-γ, and TNFα 1 day post-stroke." (PMID 28659854, 2017). "This indicates a deleterious role of TNF-α in stroke progression in these animal models." (PMID 28115020, 2017). "There is increasing evidence that P2Y1R plays a role in astrocytes/macrophages–mediated neuroinflammation, which could lead to positively regulate transcription of inflammatory genes, such as TNF-α, IL-1β following post-stroke cognitive impairment." (PMID 29017492, 2017). "A significant decrease in TNF-α levels and nitrosative stress corroborate our findings related to protective effects against inflammatory cytokine and nitrosative stress induced neuronal cell death and post stroke complications." (PMID 28615993, 2017). "TNF-α is increased in the serum of stroke patients between 6 and 12 h after symptom onset." (PMID 28115020, 2017). "A recent meta-analysis indicated that XNJ could significantly increase efficacy rate, decrease neurological deficit scores and the serum level of TNF-α of the patients of stroke." (PMID 28912713, 2017). "Moreover, serum levels of TNF-α and IL-6 decreased, whereas IL-10 increased in stroke patients between day 1 and day 3 (all p < 0.05)." (PMID 27682880, 2017). "Inhibition of inflammation with a TNF-α antibody in exercised animals reversed improvements in neurological outcome and infarct volume after stroke, supporting previous findings that TNF-α signaling plays a critical role in ischemic tolerance induced by preconditioning." (PMID 27492770, 2016). "However, after sex stratification we found that IL1A, IL1B, IL6, IL8, TNF and other 13 anti-stroke targets were all up-regulated in male patients." (PMID 27672514, 2016).